SPIN1 (spindlin 1)
Diseases named in the same sentence as SPIN1 in open-access papers (continued):
Sharing a sentence is not in itself a finding about the gene and the disease.
colorectal cancer (3 papers, 2018 to 2025). A primary or metastatic malignant neoplasm that affects the colon or rectum. "Nevertheless, the cellular functions and clinical significance of SPIN1, along with the mechanism underlying its dysregulation in colorectal cancer, remain poorly characterized." (PMID 34753384, 2021). "In colorectal cancer, SPIN1 promotes tumor cell proliferation and invasion by activating the Wnt/β-catenin signaling pathway." (PMID 40567896, 2025). "MiR-381 impedes colorectal cancer cell proliferation and invasion through inactivation of the Wnt/β-catenin pathway via targeting SPIN1." (PMID 34753384, 2021). "Our study aimed to investigate the clinical significance and biological functions of Spindlin1 (SPIN1) in colorectal cancer (CRC) tumorigenesis and progression, as well as the mechanism underlying its upregulation." (PMID 34753384, 2021). "In this study, our data showed that miR-381 inactivates the Wnt/β-catenin signaling pathway by targeting SPIN1, and therefore represents an actionable therapeutic target for colorectal cancer patients." (PMID 34753384, 2021). "Interestingly, our analysis of TCGA genome database indicated that the SPIN1 gene is markedly amplified in a panel of cancers, including prostate, sarcoma, lung, stomach, breast, head and neck, pancreas and colorectal cancers." (PMID 29547122, 2018). "In summary, our data revealed that the miR-381/SPIN1 axis greatly contributes to CRC tumorigenesis by orchestrating the Wnt/β-catenin pathway, thereby representing actionable therapeutic targets for colorectal cancer patients." (PMID 34753384, 2021).
liver cancer (3 papers, 2021 to 2022). An epithelial or non-epithelial malignant neoplasm that arises from the liver. "Analysis of liver cancer tissue samples provided evidence of higher expression of SPIN1 than peritumor tissue samples." (PMID 34552769, 2021). "The SPIN1 stimulates the growth of liver cancer via the SREBP1c-triggered FASN signaling pathway." (PMID 34552769, 2021). "SPIN1 triggers FASN signals through SREBP1c to regulate abnormal liver lipid metabolism and promote liver cancer cell growth." (PMID 35070947, 2021).
lung carcinoma (3 papers, 2021 to 2024). "The expression of SPIN1 was obviously elevated in lung cancer tissues and cell lines compared with normal tissues and Beas-2B cells, implying that SPIN1 is a crucial factor in NSCLC progression." (PMID 39548064, 2024). "As expected, depletion of SPIN1 inhibited the growth of lung cancer cells in the silenced group compared with that in the control group." (PMID 39548064, 2024). "For example, knocking down circ_0086720 increased radiosensitivity in lung cancer by modulating the miR-375/SPIN1 axis." (PMID 36899354, 2023). "In addition, IHC assays revealed that the level of SPIN1, located mainly in the nucleus, was greater in lung cancer tissues than in adjacent normal tissues (86/120, 71.6%)." (PMID 39548064, 2024). "Next, we quantified SPIN1 protein expression in 8 fresh NSCLC tissues and matched adjacent nontumor tissues, as well as 7 human lung cancer cell lines." (PMID 39548064, 2024).
prostate carcinoma (3 papers, 2021 to 2025). A carcinoma that arises from epithelial cells of the prostate gland. "In this context, differences in protein expression (SATB1, SPIN1, TBB5, VIME, TPM4) between benign prostate tissue and prostate cancer with respect to clinicopathological risk factors, tumor heterogeneity and genomic instability were assessed." (PMID 34961766, 2021). "Despite their tumor biology functions, neither SATB1, SPIN1, VIME, TBB5 nor TPM4 are yet being used in routine risk assessment for prostate cancer." (PMID 34961766, 2021).
cervical carcinoma (2 papers, 2018 to 2025). A carcinoma arising from either the exocervical squamous epithelium or the endocervical glandular epithelium. "In line with this, we observed similar patterns in HeLa cervical carcinoma cells overexpressing SPIN1 and SPIN3, but not in HEK293T cells, which do not originate from a tumor." (PMID 30197756, 2018).
colon cancer (2 papers, 2018 to 2024). "Western blot analysis of a panel of human colon cancer samples revealed that SPIN1 is expressed at significantly higher levels in tumors than in normal tissues." (PMID 29547122, 2018). "Remarkably, knockdown of SPIN1 inhibited xenograft tumorigenesis derived from human colon cancer cells, which was much more significantly in HCT116p53+/+ cells than in HCT116p53-/- cells." (PMID 29547122, 2018).
glioma (2 papers, 2018 to 2022). A benign or malignant brain and spinal cord tumor that arises from glial cells (astrocytes, oligodendrocytes, ependymal cells). "It has been reported that miR-489 can promote apoptosis in glioma cells via inhibiting the SPIN1-priming PI3K/AKT pathway." (PMID 35572727, 2022).
hepatocellular carcinoma (2 papers, 2021). A malignant tumor that arises from hepatocytes. "SPIN1 modulates abnormal lipid metabolism by increasing intracellular cholesterol, triglycerides, and lipid droplets in hepatoma cells." (PMID 34552769, 2021).
lymph node metastasis (2 papers, 2020 to 2021). "More interestingly, we found that SPIN1 expression in GC with LNM was significantly higher than that without LNM, suggesting that SPIN1 may be associated with lymph node metastasis in GC." (PMID 32767629, 2020). "SPIN1 expression was strongly correlated with depth of invasion (p = 0.01), clinical TNM stage (p = 0.002), and lymph node metastasis (p = 0.004)." (PMID 34753384, 2021).
melanoma (2 papers, 2018 to 2020). A malignant, usually aggressive tumor composed of atypical, neoplastic melanocytes. "In our previous report, we have demonstrated that lncRNA MHENCR competitively binds miR-425 and miR-489, and therefore upregulates their targets IGF1 and SPIN1 in melanoma." (PMID 34094894, 2020).
seminoma (2 papers, 2018 to 2021). A radiosensitive malignant germ cell tumor found in the testis (especially undescended), and extragonadal sites (anterior mediastinum and pineal gland). "Given that TCam-2 male germ cells originate from a seminoma, we hypothesized that SPIN1 is a proto-oncogene and SPIN3 is a tumor suppressor in these cells." (PMID 30197756, 2018). "Furthermore, Spin1 expression was elevated in some types of cancers, including the seminoma." (PMID 34526015, 2021). "The present study describes two proteins, SPIN1 and SPIN3, that play opposite roles in regulating apoptosis in the human seminoma (a type of TGCT) cell line, TCam-2." (PMID 30197756, 2018). "Here, we investigated the functional significance of SPIN1 and its structurally similar paralogue, SPIN3, with respect to apoptosis and cell cycle progression in the human seminoma cell line, TCam-2." (PMID 30197756, 2018). "Here, we examined the functional significance and regulation of SPIN1 and SPIN3 in the TCam-2 human seminoma cell line." (PMID 30197756, 2018).
alcoholic pancreatitis (1 paper, 2009). Acute or chronic inflammation of the pancreas due to excessive alcohol drinking. "However, studies of the fibrogenesis and genetic modifications of alcoholic pancreatitis have improved our knowledge of this disease, demonstrating that SPIN-1 and CFTR gene modification may act as modifier genes." (PMID 20049222, 2009).
autoimmune disease (1 paper, 2022). A disorder resulting from loss of function or tissue destruction of an organ or multiple organs, arising from humoral or cellular immune responses of the individual to their own tissue constituents. "Pld1 inhibitors reportedly promote Treg differentiation in vitro to improve the validation response in autoimmune diseases; the effect of Spin1 on the proliferation and migration of tumor cells has been demonstrated in most tumor studies whereas studies on immune function have been rarely reported." (PMID 35874774, 2022).
gastric tumor (1 paper, 2020). "Furthermore, analysis of The Cancer Genome Atlas (TCGA) genome database indicates that SPIN1 expression is markedly elevated in human gastric tumor samples compared with normal tissues, indicating that SPIN1 may play an oncogenic role in GC progression." (PMID 32767629, 2020).
lipoma (1 paper, 2015). A benign, usually painless, well-circumscribed lipomatous tumor composed of adipose tissue. "Screening tumor tissue arrays by immunohistochemistry with a SPIN1-specific antibody, we observed elevated SPIN1 protein levels in WDLS, MLS, DDLS, and PLS compared to normal adipose tissue or lipoma (Supplementary 1A–1C)." (PMID 25749382, 2015). "Furthermore, staining of adipose tissue, lipoma, WDLS, MLS, DDLS, or PLS samples taken from one patient with SPIN1, GNDF, RETph, or MAZ antibody showed that also in individual patients high levels of SPIN1 correlate with high levels of GDNF, RETph, or MAZ." (PMID 25749382, 2015).
lung adenocarcinoma (1 paper, 2024). A carcinoma that arises from the lung and is characterized by the presence of malignant glandular epithelial cells. "Notably, significant associations between SPIN1 expression and clinical TNM stage, tumour size, depth of invasion, and lymph node metastasis were detected in the analysis of paraffin-embedded lung adenocarcinoma tissues (p < 0.05)." (PMID 39548064, 2024).
psoriasis (1 paper, 2022). An autoimmune condition characterized by red, well-delineated plaques with silvery scales that are usually on the extensor surfaces and scalp. "Some psoriasis loci showed a substantial single-tissue eQTL, primarily in the cardiovascular system (artery coronary: rs240993/KIAA1919, rs9808753/TMEM50B, heart left ventricle: rs11053802/KLRC4, heart left ventricle: rs11053802/KLRK1, rs5063/CLCN6, rs1050414/HLA-B, rs2778031/SPIN1)." (PMID 36320003, 2022).
sterility (1 paper, 2024). "Several miRNAs interacting with the 3′ UTR of target genes have been reported to affect traits in fish, such as aberrant expression of miR-1388-5p, which was associated with sterility in triploid rainbow trout by repressing the expression of spindlin-1." (PMID 39765543, 2024).
cancer (31 papers, 2015 to 2026). A tumor composed of atypical neoplastic, often pleomorphic cells that invade other tissues. "By analyzing cancer mutation data from the cBioPortal database, we found that the presence of deletions or missense mutations on SPIN1 in cancer cases correlates with a poor patient survival rate." (PMID 38777743, 2024). "Spindlin1 (SPIN1) is an extremely expressed protein in various cancer types and is also associated with tumor development and genesis." (PMID 34589423, 2021). "This spindle-binding protein is necessary for the meiotic progression of germ cells, while abnormal overexpression of SPIN1 is associated with human ovarian cancers and has been observed in some other cancer cell lines." (PMID 33401540, 2021). "It is known that SPIN1 is a histone code reader highly expressed in several types of cancers and strongly implicated in tumorigenesis and tumor growth." (PMID 28423652, 2017). "Furthermore, SPIN1 is overexpressed in several varieties of malignant tumors and upregulation of SPIN1 is known to increase cellular proliferation and cause chromosomal instability and abnormal mitosis." (PMID 28293301, 2017). "In this study we aimed to clarify the role of H3K4me3 binding of SPIN1 on a genome-wide scale and evaluate whether targeting SPIN1 chromatin association is a potential therapeutic strategy in cancer." (PMID 25749382, 2015). "Spindlin-1 inhibitors are being studied for their potential therapeutic applications, particularly in cancer treatment, as Spindlin-1 is known to be overexpressed in various cancer types." (PMID 40512144, 2025). "We investigated the relationship between SPIN1 expression and cancer cell metastasis, including EMT score and angiogenesis score." (PMID 40567896, 2025). "Since cancer drugs often exert immune-suppressive effects, we were interested to know if Spindlin-1 inhibitors also modulate the immune response." (PMID 40512144, 2025). "The tandem Tudor-like domain-containing protein Spindlin1 (SPIN1) is a transcriptional coactivator with critical functions in embryonic development and emerging roles in cancer." (PMID 39090319, 2024). "Accumulating reports have demonstrated the upregulation of SPIN1 in various cancer tissues, implicating its role in promoting cancer cell proliferation and tumorigenesis." (PMID 38777743, 2024). "Previous studies have shown that SPIN1 was essential for cell cycle redistribution and that SPIN1 downregulation sensitised cancer cells to DNA damage." (PMID 39548064, 2024). "SPIN1 has been extensively studied for its role as a transcriptional coactivator in embryonic development and its implications in cancer." (PMID 39090319, 2024). "Our results showed that knockdown of SPIN1 increased the sensitivity of cancer cells to Cisplatin and Olaparib, while reintroducing SPIN1 restored their resistance to these drugs." (PMID 39090319, 2024). "The findings of our study provide important insights into not only the role of SPIN1 in DNA damage repair but also its potential implications in cancer chemoresistance." (PMID 39090319, 2024). "SPIN1 is also involved in cell-cycle regulation, chromosome stability, multinucleated giant cell formation, cancer cell proliferation and metastasis, and abnormal tumor lipid metabolism." (PMID 38777743, 2024). "It has been extensively reported that SPIN1 is highly expressed in various types of cancers, suggesting its potential role as a tumor promoter." (PMID 39090319, 2024). "Previous studies also reported the potential of small-molecule inhibitors that target the ‘rigid’ Tudor-like 1 and Tudor-like 2 domains of SPIN1 in cancer treatment." (PMID 38777743, 2024).
cancer (continued). "Identifying SPIN1 as a key player in H3K9me3-dependent DNA repair pathways emphasizes its potential as a promising therapeutic target for cancer treatment." (PMID 39090319, 2024). "Accumulating evidence indicates that SPIN1 promotes tumorigenesis by activating multiple cancer-related downstream signaling pathways, such as the Wnt, PI3K/AKT, and RET pathways." (PMID 39090319, 2024). "It is crucial to explore strategies such as inhibiting the binding of SPIN1 to H3K9me3 or targeting SPIN1 itself to suppress DNA damage repair, thereby sensitizing cancer cells with high SPIN1 expression to DNA-damaging drugs." (PMID 39090319, 2024). "Mounting evidence has demonstrated that dysregulation of SPIN1 contributes greatly to cancer tumorigenesis and progression in a series of tumors." (PMID 34753384, 2021). "SPIN1 also stimulated cell cycle progression in our study, as was previously reported in other types of cancers." (PMID 30197756, 2018). "SPIN1 (also known as SPINDLIN1) was selected as a candidate mRNA target for PUM1 via a RIP-Chip screening of human HeLa cancer cells, as it binds PUM1 and contains several PBE-like motifs in its 3′UTR." (PMID 30197756, 2018). "Analysis of cancer genomic databases suggests that SPIN1 is highly expressed in several human cancers, and its overexpression is positively correlated with poor prognosis in cancer patients." (PMID 29547122, 2018). "Spindlin-1, a multivalent epigenetic reader, is a new target for cancer therapy." (PMID 40512144, 2025). "Then we evaluated the SPIN1 expression and cancer cell proliferation." (PMID 40567896, 2025). "We used TCGA-STAD database to explore the expression levels of SPIN1 in normal and cancer tissues." (PMID 40567896, 2025). "Excessive levels of SPIN1 may have detrimental effects on spindle microtubule organization and chromosomal stability, potentially contributing to cancer development." (PMID 39090319, 2024). "SPIN1 has been extensively studied for its role as a histone methylation reader and a transcriptional coactivator that facilitates the expression of rRNA genes, embryonic development and its implications in cancer." (PMID 39090319, 2024). "Our findings suggest that targeting SPIN1 could be a potential strategy to enhance the sensitivity of cancer cells to DNA damage-inducing agents, including IR and anticancer drugs." (PMID 39090319, 2024). "Targeting SPIN1 could potentially enhance the efficacy of DNA repair-based therapies and overcome chemoresistance in cancer patients." (PMID 39090319, 2024). "Importantly, our results also demonstrate that SPIN1 confers chemoresistance to DNA-damaging drugs in cancer cells." (PMID 39090319, 2024). "Given that SPIN1 promotes transcription of rRNA genes, it is reasonable to assume that its overexpression in many human cancers facilitates ribosome biogenesis to support the rapid growth and proliferation of cancer cells." (PMID 39090319, 2024). "Furthermore, SPIN1 is highly expressed in various types of cancers, suggesting its potential role as a tumor promoter." (PMID 39090319, 2024). "Considering the significance of DNA damage response in chemoresistance, we investigated whether SPIN1 may contribute to cancer chemoresistance by affecting the efficiency of DSB repair." (PMID 39090319, 2024). "Our in-depth study on the ‘flexible mechanism’ of SPIN1 function not only reveals a novel mechanism for SPIN1 function but also provides a new perspective for drug design and development for cancer treatment, which is highly valuable in both academic research and biomedical application." (PMID 38777743, 2024).